CRP (C-reactive protein)
Diseases named in the same sentence as CRP in open-access papers (continued):
Sharing a sentence is not in itself a finding about the gene and the disease.
cancer (continued). "This may be due to either the small sample size or the strong association between CRP and metastasis; nodal disease was the only significant predictor of cancer-related death in both uni- and multivariate analyses." (PMID 23642165, 2013). "Thus, due to the characteristics of simplicity, cost-effectiveness and availablility in daily practice and the association with cancers, the measurement of serum C-reactive protein (CRP) levels has gained increasing attention." (PMID 24255664, 2013). "The question was raised as to whether the CRP value might help to distinguish between inflammation and cancer spread as the cause of nodal enlargement." (PMID 24148787, 2013). "Furthermore, a high CRP value was associated with poor cancer specific survival in patients undergoing resection for UUT-UC." (PMID 23497335, 2013). "One hypothesis states that elevated levels of CRP are a marker of an underlying cancer or a premalignant state." (PMID 22912790, 2012). "However, in most studies, CRP levels were measured well before development of cancer, so that associations were seen several years after CRP measurement, ruling out this causality." (PMID 22912790, 2012). "We assessed elevated YKL-40 and CRP levels as combined risk predictors for cancer." (PMID 22095223, 2012). "On univariate cancer-specific survival analysis, performance status (P<0.10), T stage (P<0.001), tumour size (P<0.10), grade (P<0.001), necrosis (P<0.01), C-reactive protein (P<0.001) and mGPS (P<0.001) were significantly associated with cancer-specific survival." (PMID 22166802, 2012). "Indeed, measurement of the systemic inflammatory response, particularly CRP, has been included in the definition of cancer cachexia, together with weight loss and reduced calorie intake." (PMID 22103888, 2011). "It is also recognised that patients with cancer may have concurrent morbidity causing a rise in their C-reactive protein and derangement of their albumin and other biochemical parameters." (PMID 21266974, 2011). "The CRP levels were inversely associated with survival in American Joint Committee on Cancer stage II patients (P=0.038), suggesting that CRP could be used to support treatment decisions in this subgroup." (PMID 21081932, 2011). "Simple measures of immune responsiveness include simple routine biochemical and haematological markers such as total and differential leukocyte counts and C-reactive protein (CRP), which have been proposed as diagnostic and prognostic factors for a variety of cancers." (PMID 20053279, 2010). "There were similar interrelationships in the cancer cohort with the strongest associations (Spearman's correlation ⩾0.3) existing between C-reactive protein and albumin, C-reactive protein and Alk phos, bilirubin and AST, Alk phos and GGT, AST and ALT, AST and GGT and ALT and GGT." (PMID 20717110, 2010). "A review of the recent literature reveals multiple studies proposing a predictive value for acute-phase CRP; including the prediction of all-cause hospital mortality, death and complications in various critical care scenarios, cancer relapse, and the progression of inflammatory arthritis." (PMID 20877716, 2010). "Single measurements of CRP or L-CRP have previously been used to correlate with the risk of certain cancers, prognosis or cancer recurrence and occasionally these have been repeated weeks or months apart to determine any persistence or trends in CRP levels." (PMID 19948067, 2009). "TNM stage (HR 1.37, 95% CI 1.01–1.87, P=0.0426), treatment (HR 3.67, 95% CI 1.74–7.75, P=0.0006), appetite loss (HR 1.02, 95% CI 1.01–1.03, P<0.0001) and C-reactive protein (HR 2.15, 95% CI 1.21–3.83, P=0.0091) were independently associated with cancer-specific survival." (PMID 18268490, 2008).
cancer (continued). "In the present study C-reactive protein concentrations, at the time of quality of life assessment, were available in 94 patients (57 patients <10 mg l−1, 37 patients >10 mg l−1) and were significantly associated with poorer cancer-specific survival (P<0.0001)." (PMID 18268490, 2008). "Moreover, we have shown that an elevated C-reactive protein concentration, before surgery, is associated with poor cancer-specific survival in patients undergoing potentially curative resection for gastro-oesophageal adenocarcinoma." (PMID 16685271, 2006). "On multivariate analysis of these significant factors, stratified by stage, only C-reactive protein (HR 2.89, 95% CI 1.42–5.91, P=0.004) and adjuvant therapy (HR 0.29, 95% CI 0.14–0.62, P=0.001) were independently associated with poorer cancer-specific survival." (PMID 17024120, 2006). "In summary, the results of the present study shows that, in addition to grade and Ki-67 labelling index, both local (tumour COX-2 expression) and systemic (C-reactive protein) markers of the inflammatory response were associated with poor cancer-specific survival." (PMID 17024120, 2006). "Also, stage (P<0.001), grade (P<0.001) and elevated C-reactive protein preoperatively (P<0.05) and postoperatively (P<0.01) were significantly associated with cancer-specific survival." (PMID 15726119, 2005). "Also, stage (HR 3.37, 95% CI 1.37–8.29, P=0.008), grade (HR 2.01, 95% CI 1.14–3.57, P=0.017) and preoperative C-reactive protein (HR 3.31, 95% CI 1.09–10.09, P=0.035) were independently associated with cancer-specific survival." (PMID 15726119, 2005). "Furthermore, neither sIL-6R nor sgp130 concentrations were significantly associated with either IL-6 or C-reactive protein concentrations in the cancer patients." (PMID 15570310, 2004). "However, further investigation is required to ascertain whether elevated CRP levels occur prior to the biological onset of cancer or whether they act as a risk factor for its onset." (PMID 40076898, 2025). "Furthermore, a study conducted in patients with advanced CKD and cancer has also shown an association between increased C-reactive protein and ESA hyporesponsiveness, thus underlining the role of chronic inflammation in determining ESA hyporesponsiveness in CKD." (PMID 40126283, 2025). "Furthermore, critical values such as very low Hb (OR 2.8), very high CRP (OR 3.6), very high B12 vitamin (OR 3.2), and very high total (OR 5.6) and ionised calcium (OR 1.8) were associated with cancer, but values such as very low eGFR and very high HbA1c were not." (PMID 38409600, 2024). "Therefore, our findings further substantiated the causality of CRP with deaths other than cancer." (PMID 39460870, 2024). "CRP is produced by the hepatocytes in response to the release of the inflammatory cytokines, e.g., interleukin 6 (IL-6), and high concentration (>10 μg/mL) has been associated with advanced cancer stages, metastasis, and poor prognosis in different cancer types including NSCLC." (PMID 38001689, 2023). "Whether serial CRP measurements may help identify high-risk individuals from the general population and whether specific anti-inflammatory therapy in such individuals would also reduce the development of cardiovascular and cancer events remain to be studied." (PMID 37019514, 2023). "In light of mechanistic insights into the association between reduced ApoA1 and the increased risk of cancer mortality, a significant inverse correlation between the extent of chronic systemic inflammation represented by hs‐CRP level and ApoA1 might be a possible explanation in our study." (PMID 35796324, 2022). "In addition, the findings also indicate that AL (with components assessing HDL and CRP) may be a useful biomarker predictive of cancer risk." (PMID 35804816, 2022).
cancer (continued). "Hence, exploring the non-linear relationship between CRP concentration and cancer risk in observational studies and MR analysis, simultaneously, might provide new knowledge for understanding CRP concentration and cancer risk." (PMID 36117174, 2022). "Besides, similar results were also observed in the sensitivity analyses of re-estimating the association between log-transformed CRP concentration and cancer risks, re-evaluating in individuals of genetically confirmed British ancestry, or using rs2794520 as an instrument variable." (PMID 36117174, 2022). "Thus, inflammation induced by cancer may explain the observed associations between appetite and albumin, CRP, fatigue, and pain." (PMID 35629338, 2022). "Moreover, CRP is known as a biomarker of frailty, is linked to sarcopenia, functional decline, increased risk of toxicity, decreased QoL, and higher mortality in older adults with different types of malignancies." (PMID 36233472, 2022). "In conclusion, sleep disruption may lead to abnormal inflammatory responses as evidenced by the upregulation of proinflammatory cytokines (especially IL-6 and CRP), which are potential risk factors for several cancers, including ovarian, brain, breast and colorectal cancers." (PMID 35246220, 2022). "Moreover, an elevated-serum CRP is closely related to the risk of malnutrition and neoplastic cachexia, leading to increased mortality and reduced effectiveness of therapies in patients with cancer." (PMID 36612251, 2022). "Besides age, frailty and disease stage, a preoperative elevated plasma level of CRP might help in detecting older cancer patients who are at risk for poor outcome after surgery." (PMID 33920422, 2021). "However, counterintuitively, cancer patients also had higher Bacteroidota/Firmicutes_A ratios, which are associated with features of good health such as lower BMI, alanine aminotransferase, and C-reactive protein, as well as greater stability." (PMID 33175106, 2021). "In addition, gastrointestinal disease type was not linked to SARC-F ≥4 points as a significant factor, while age, gender, serum albumin, lymphocyte count, CRP, and the presence of advanced cancer were significant factors linked to SARC-F ≥4 points in the multivariate analysis." (PMID 34575208, 2021). "Different gene polymorphisms of CRP and inflammatory cytokines or biological mechanisms implicated in inflammatory process have been explored with heterogeneous concluding data, depending the type of gene polymorphism and the type of cancer, mainly in colorectal cancer." (PMID 33708198, 2021). "Furthermore, the Hb level was inversely correlated with interleukin-6 expression, oxidative stress markers, and C-reactive protein level among patients with advanced cancer, which implied that inflammatory status is associated with worse iron metabolism in advanced cancers." (PMID 34034691, 2021). "However, given the higher frequency of a large tumor size and vascular invasion, cancer progression may contribute to increase the poor prognostic risk in patients with the CRP/Alb>0.089." (PMID 32856868, 2020). "Moreover, patients with (locally) advanced cancer are mostly associated with considerably increased plasmatic levels of CRP, which may confirm the closed relationship between cancer and chronic inflammation." (PMID 31936329, 2020). "The mechanism behind this association between CRP and cancer prognosis remains largely unknown." (PMID 33351844, 2020). "Cancer- related pro-inflammatory cytokines, in particular IL-1 and IL-6, have been linked with the stimulation of CRP production; thus, increased CRP levels may represent an inflammatory microenvironment that supports tumor angiogenesis, proliferation, growth, and metastasization." (PMID 33023215, 2020). "Therefore, examining whether functional CRP variants are associated with cancer risk in different populations might help to clarify the role of CRP in tumorigenesis." (PMID 32477370, 2020).
cancer (continued). "Furthermore, population studies have shown an association between CRP level and both all-cause mortality, cancer mortality and cardiovascular mortality, and CRP levels also show associations with frailty (i.e., a geriatric syndrome characterized by a physiological state of vulnerability)." (PMID 32707721, 2020). "In addition, Piwi-like 1 expression allowed to further distinguish the RCC patients with high Fuhrman grade, high tumor stage, distant metastasis or high pre-operative levels of C-reactive protein, as Piwi-like 1 positivity was associated with a shorter cancer-specific survival in both cohorts." (PMID 30741998, 2019). "There are two hypotheses that are explaining the association between CRP and cancer." (PMID 30065196, 2018). "However, it is still unclear whether CRP levels are elevated before the biological onset of cancer or if an elevated CRP level is a risk factor for the development of cancer." (PMID 30842796, 2018). "The role of HNF1α in the regulation of core versus outer arm fucosylation may be the molecular mechanism behind the reported association between common variants of HNF1α and inflammatory markers such as CRP as well as several diseases where inflammation plays a key pathogenic role such as cancer." (PMID 28657165, 2017). "This might underestimate any associations, especially between CRP and cancer." (PMID 26860264, 2016). "Therefore, it is plausible that CRP polymorphisms correlate with cancer development." (PMID 26912098, 2016). "Finally, abnormal levels of leptin and CRP may occur secondary to cancer which may result in reverse causation." (PMID 26632325, 2016). "Thus, CRP levels, in combination with reduced food intake and weight loss, could be used as a clinical marker of cancer cachexia." (PMID 26504362, 2015). "However, association data determined from these independent studies is relatively powerless; therefore, the present study conducted a meta-analysis of all eligible published studies, and the effect of CRP 3407 A>G and 29 A>T polymorphisms on cancer risk was evaluated." (PMID 25624919, 2015). "Moreover, for potential clinical application, it is important to determine whether the elevated CRP-SAA level is restricted to cancer patients or whether it is associated with other chronic inflammatory diseases." (PMID 26264146, 2015). "In addition to its role as a very sensitive indicator of current disease activity for inflammation, the role of serum CRP has recently been re-evaluated by extending its clinical use to the diagnosis of cardiovascular diseases as well as risk prediction of cancer." (PMID 24800842, 2014). "Recent studies have shown that elevated serum CRP levels may be associated with tumor size, distant metastasis, vascular invasion, lymph node metastasis and tumor recurrence, resulting in poor prognosis in patients with various cancers, including HCC." (PMID 23374755, 2013). "However, adjustment by CRP attenuated the association between IL-6 and cancer mortality." (PMID 22514624, 2012). "Thus, we first examined whether elevated levels of YKL-40 and CRP are mutually independent risk predictors for gastrointestinal, lung, and any cancer." (PMID 22095223, 2012). "Therefore, causality cannot be inferred in the association of hs-CRP with cancer risk." (PMID 21368452, 2011). "Therefore, we aim to determine whether the IRP and other inflammatory markers (Interleukin-6 (IL-6); Tumour necrosis factor-α (TNF-α); C-reactive protein (CRP)) are associated with wellbeing/mortality in older cancer patients." (PMID 22026575, 2011). "However, it is still unclear whether CRP levels are elevated before the biological onset of cancer or if an elevated CRP level is also a risk factor for the development of cancer." (PMID 20673375, 2010). "However, until very recently, a paucity of information was available as to whether CRP can serve as a prognostic or diagnostic factor in cancer." (PMID 19341447, 2009).
cancer (continued). "C-reactive protein is recognised to be an activator of innate immunity and a modulator of adaptive immunity and its elevation is a precursor to progressive involuntary loss of weight and lean tissue, which are believed to be key factors in determining cancer survival." (PMID 17024120, 2006). "When C-reactive protein was excluded from the multivariate analysis, stratified by stage, only Ki-67 labelling index (HR 1.56, 95% CI 0.99–2.45, P=0.045) and adjuvant therapy (HR 0.41, 95% CI 0.19–0.86, P=0.019) were independently associated with poorer cancer-specific survival." (PMID 17024120, 2006). "Several studies have also shown that C-reactive protein (CRP), albumin levels, neutrophil-to-lymphocyte ratio (NLR), and platelet-to-lymphocyte ratio (PLR) are associated with cancer stage." (PMID 41585333, 2026). "Background/Objectives: The vitamin B12 (VB12)/C-reactive protein (CRP) index (BCI), a clinically derived index calculated as serum VB12 multiplied by CRP, has shown prognostic value in several cancers." (PMID 42193456, 2026). "BACKGROUND: As a novel inflammatory-nutritional biomarker, the C-reactive protein–albumin–lymphocyte (CALLY) index has demonstrated significant prognostic value in several cancer types." (PMID 42032543, 2026). "In the subgroup analyses, we further explored how CRP levels and alcohol consumption influenced the associations of LE8 with cancer risks." (PMID 41554683, 2026). "The CALLY index, based on C - reactive protein, albumin, and lymphocyte levels, has shown potential in predicting cancer prognosis and guiding treatment." (PMID 41798270, 2026). "Among them, C-reactive protein (CRP), a widely recognized acute-phase protein, has demonstrated considerable utility in prognostic evaluation across multiple cancer types." (PMID 41566198, 2026). "Multinomial regression was used to evaluate the role of the predictor (salivary CRP levels) on the outcome (cancer/OPMDs) adjusting for sex and age." (PMID 39851610, 2025). "A recent study showed that high CRP levels at the initiation of ICI therapy were associated with significantly reduced OS and PFS across various cancer entities." (PMID 41009716, 2025). "Herein, we developed a machine learning (ML) model, i.e., Alertix-Cancer Risk Index (Alertix-CRI) which incorporates canine TK1 protein, CRP levels in conjunction with an age factor." (PMID 40351765, 2025). "Elevated CRP levels are often observed in cancer patients due to tumor‐induced inflammation and immune response dysregulation." (PMID 40927964, 2025). "Omega-3 supplementation in cancer patients reduces inflammatory markers such as IL-6 and C-reactive protein (CRP) and improves inflammation-based prognostic scores." (PMID 40808836, 2025). "Blood CRP levels are commonly used to monitor inflammation and cancer progression in affected individuals." (PMID 40420174, 2025). "Essentially, the elevation of CRP due to inflammation sets the stage for tumorigenesis by creating a hospitable environment for cancer cells." (PMID 39980561, 2025). "The CALLY Index, integrating albumin, lymphocyte count, and CRP, stands out as an emerging marker with demonstrated prognostic importance in several cancers like gastric, colorectal, and Non-Small Cell Lung Cancer (NSCLC)." (PMID 40034601, 2025). "Although previous studies have demonstrated the prognostic utility of the CRP-albumin-lymphocyte (CALLY) index in various cancer types, data regarding its role in metastatic renal cell carcinoma (mRCC) remain limited." (PMID 40836295, 2025). "Our prior work shows that systemic inflammation in humans with cancer, assessed by circulating C‐reactive protein (CRP) levels, is related to the presence of leukocytes within muscle." (PMID 41243421, 2025). "Evidence suggests that atorvastatin significantly reduces IL-6 and CRP levels in cancer patients, and other research has confirmed statin-mediated CRP reduction across various diseases and cell types." (PMID 40943351, 2025).